TGFB1 (transforming growth factor beta 1)
Diseases named in the same sentence as TGFB1 in open-access papers (continued):
Sharing a sentence is not in itself a finding about the gene and the disease.
tumor (continued). "A paracrine effect of tumour cell-derived TGFβ1 on the down-regulation of gap junctional intercellular communication between stromal fibroblasts was shown earlier, dependent on the generation of ROS (reactive oxygen species)." (PMID 27919042, 2014). "In the tumor microenvironment, TGFβ1 is produced by a variety of cells and acts as an intercellular signaling molecule that induces the expression of cytokines and angiogenic factors, which consequently promote tumor growth, invasion and metastasis." (PMID 25202359, 2014). "The over-expression of TGFβ1 promotes tumor growth and aggressive pulmonary metastasis during the late stages of lung carcinogenesis." (PMID 25149540, 2014). "Osteopontin, a secreted phosphoprotein implicated in tumor metastasis both mechanistically and as a marker, is able to induce MSCs to adopt a CAF phenotype through autocrine signaling of TGFβ-1." (PMID 25343018, 2014). "During tumor development, TGFβ1 binds to TGFβRII, initiating a signaling transduction that culminates in cell cycle control and induction of apoptosis." (PMID 25909813, 2014). "For instance, transforming growth factor beta-1 has been known to act, in a context-dependent manner, as an oncogene or a tumor suppressor." (PMID 24371278, 2014). "In PDAC, TGFβ1 acts as a tumor suppressor by inhibiting cancer cell growth, and as a tumor promoter by dampening host immune surveillance while inducing an epithelial to mesenchymal transition (EMT) and a stromal expansion." (PMID 24670043, 2014). "Generally, the tumor promoter function of TGFβ1 in the context of cancer progression results from two actions including losing its inhibitory effect on carcinogenesis and awaking its oncogenic function." (PMID 25162823, 2014). "XPO4 in cancerous liver tissue (CC=0.143, P=0.035) and TGFβ1 (CC=0.195, P=0.004) in paracancerous liver tissue were significantly correlated with tumor differentiation." (PMID 23251252, 2013). "HRS cells produce activated TGFβ1 in primary tumor tissues, predominantly in nodular sclerosing HL, while MMP9 overexpression is associated with adverse clinical outcomes in HL." (PMID 23988031, 2013). "In vitro studies have shown that in PC cells, the TGFβ1 signaling pathway has some defects and the restoration of this pathway can suppress tumor growth by inhibiting cell proliferation." (PMID 23951322, 2013). "Studies have demonstrated that CAFs are significant promoters of tumour growth and progression via growth factors, including TGFβ1 and HGF, which are secreted by the CAFs themselves and/or by carcinoma cells." (PMID 24137336, 2013). "Overall, our findings demonstrate for the first time that km23-1 regulates not only CRC cell migration, invasion, and tumor growth, but also critical markers of a pro-invasive phenotype, including TGFβ1, Ezrin, and ERK." (PMID 23755307, 2013). "TGFβ1 was strongly expressed by both tumors and cell lines, suggesting that tumor cells are a major source of this cytokine." (PMID 23982484, 2013). "In connection with patients’ clinical and revisit information, statistical results revealed that TGFβ1 levels in paracancerous liver tissue was positively correlated with the tumor size." (PMID 23251252, 2013). "Flow cytometry analysis of the cells irradiated with 4 Gy and treated with TGFβ1 revealed significantly lower ALDH+ tumor progenitor population in the cells overexpressing 14-3-3σ Ser74Ala mutant protein when compared to other cell types." (PMID 23741479, 2013). "TGFβ1 has also been shown to induce the epithelial-to-mesenchymal transition, which has a crucial role in the invasion and metastasis of some types of tumor cells." (PMID 23840350, 2013). "Specifically with regard to human CRC, we have shown that TGFβ1 production requires c-Fos activation, which can be targeted to decrease tumor progression in vivo." (PMID 23755307, 2013).
tumor (continued). "Preclinical studies show that inhibition of TGFβ1 signaling downregulates the migration of tumor cells and suppresses the development of metastasis." (PMID 23840350, 2013). "One potential molecular biomarker for predicting treatment outcome after radiochemotherapy for NSCLC, in terms of both tumor response and normal tissue damage, is transforming growth factor β1 (TGFβ1)." (PMID 23840350, 2013). "The TGFβ1 and its receptors are key components of the TGFβ signaling pathway, which has an important role in carcinogenesis and tumor progression." (PMID 23951322, 2013). "Explorations of the prognostic value of TGFβ1 SNPs in a variety of cancer types suggest that some TGFβ1 genotypes predict more aggressive tumor phenotypes and adverse prognosis." (PMID 23840350, 2013). "XPO4 in cancerous liver tissue and TGFβ1 in paracancerous liver tissue were positively correlated with tumor differentiation." (PMID 23251252, 2013). "As such, HRS cells that harbor the FGF2+/SDC1+ immunophenotype and express both MMP9 and TGFβ1 are the cells most likely to be shed from the tumor microenvironment." (PMID 23988031, 2013). "In connection with patient clinical and revisit information, statistical analysis determined that TGFβ1 in paracancerous liver tissue was positively correlated with tumor size." (PMID 23251252, 2013). "The statistical results revealed that the expression of TGFβ1 in paracancerous liver tissue was significantly positively correlated with tumor size (CC=0.147, P=0.021, n=248)." (PMID 23251252, 2013). "The observation that this is enhanced when receptor signaling is blocked suggests that other pathways are activated in the tumor cells or that effects of TGFβ1 on the tumor microenvironment predominate, where elevated TGFβ1 leads to significant inflammation." (PMID 23326666, 2012). "TGFβ1 contributes to many aspects of tumor development including metastasis, endothelial cell permeability, inflammation and fibrosis, all of which are altered in the absence of stromal-derived SPARC." (PMID 22348081, 2012). "This is important because TGFβ1 has been shown to have a dichotomous effect on tumor cell proliferation and migration depending on the epithelial versus mesenchymal nature of the cell." (PMID 22348081, 2012). "The TSP-1 3TSR (that is, all three TSRs of the type 1 repeat domain) can activate transforming growth factor beta 1 (TGFβ1) and inhibit endothelial cell migration, angiogenesis, and tumor growth." (PMID 22509329, 2012). "Instead, TGFβ1 induces the migration and proliferation of mesenchymal-like fibroblastoid tumor cells." (PMID 22348081, 2012). "We conclude that TGFβ1 is a significant driver of the increased tumor dissemination and decreased survival observed in tumor-bearing SPARC−/− animals." (PMID 22348081, 2012). "MEK 1 inhibitor PD 98059 reduced TGFβ1 related increase of tumour cell scattering migration and invasion [11358848] and enhances efficacy of gemcitabine." (PMID 23125850, 2012). "Other studies have shown that overexpression of TGFβ1 in xenotransplanted human SCC lines traps dendritic cells within the tumor thereby allowing escape from antitumor immunity." (PMID 23326666, 2012). "Increased levels of TGFβ1 occurs in primary keratinocytes expressing oncogenic v-RasHa, and TPA and other tumor promoters rapidly induce TGFβ1 expression in the suprabasal layers of the epidermis." (PMID 23326666, 2012). "In the tumor-stroma interactive microenvironment transforming growth factor-beta 1 (TGF-beta 1) promotes stromal fibroblast-to-myofibroblast transdifferentiation by modulating phenotypic and functional genes." (PMID 22482059, 2012). "It has been reported that TGFβ1 functions in suppressing proliferation and promoting invasion of cancer cells, indicating that TGFβ1 can serve as a tumor suppressor and a pro-metastatic factor." (PMID 22808247, 2012).
tumor (continued). "On the other hand, TGFβ1 has also been shown to promote tumor progression and metastasis of established cancers, in part by the induction of the EMT." (PMID 23185371, 2012). "We noticed that VEGFA, HIF1A, SOX4, SOX9, MMP2, TGFB1 genes are overexpressed together with S6K1 in all 4 tumour types investigated." (PMID 22570651, 2012). "In most models of epithelial cell carcinogenesis, TGFβ1 inhibits cell proliferation by arresting tumor cells in the G1 phase, thus functioning as a tumor suppressor." (PMID 23185371, 2012). "Similar affects were demonstrated for TGFβ1, which functions as a tumor suppressor in normal epithelial cells and during early stages of tumor development." (PMID 21464964, 2011). "We next investigated the effects of selective growth factors involved in vessel formation and maturation such as VEGF-A, PDGF-BB, FGF-2, TGFβ1 and conditioned media of tumor cells (A549 and PC3) on proliferation and differentiation of VW-MPSCs." (PMID 21637782, 2011). "SPARC has also been implicated in colonic polyp development and CRC tumour progression through the regulation of cycloxygenase-2 (COX-2) and transforming growth factor beta-1 (TGFβ-1)." (PMID 21818290, 2011). "In late-stage tumors TGFβ1 exhibits features of a tumor promoter, modulating vascular and immune compartments of the tumor stroma." (PMID 21464964, 2011). "Despite its role as a tumor suppressor, TGFβ1 signaling is often increased in tumor cells and induces EMT, thereby leading to tumor cell invasion." (PMID 20953359, 2010). "TGFβ1 can act in a paracrine manner to promote tumor growth and can activate PI3K/AKT, a signaling program associated with drug resistance." (PMID 20576088, 2010). "In the mouse skin model, TGFβ1 mRNA is transiently induced in response to several different tumor promoters and is constitutively overexpressed in squamous cell carcinomas." (PMID 21297902, 2010). "In summary, action of TGFβ1 on cancer cells switches from tumor suppression to tumor promotion, depending on the stage of tumorprogression." (PMID 18615188, 2008). "This was in contrast to TGFβ1 that remained high throughout and TGFβ2 that was highest in the primary tumour." (PMID 17565341, 2007). "A commonly held view is that TGFβ1 prohibits tumour cell proliferation because TGFβ1 is a potent growth inhibitor for nearly all epithelia in vitro." (PMID 16404434, 2006). "Cell proliferation, angiogenesis and the accumulation of ECM macromolecules are all facilitated by tumour cell production of TGFβ1." (PMID 15740610, 2005). "The changes in CD105 and its complex with TGFb1, as well as reduction in E selectin, are compatible with an inhibitory effect on activated tumour endothelium." (PMID 15162145, 2004). "On the other hand, the expression of TGFβ1 was found to be similar in tumours (OT and SC) and the CD18/HPAF cells." (PMID 14760381, 2004). "Immunohistochemical staining of TGFβ1 and TGFβ3 in tumour tissues revealed their distinctive expression pattern." (PMID 12778073, 2003). "With respect to TGFβ1, although published data show inconsistency, it is generally accepted that TGFβ1 acts as a tumour suppressor, particularly at an early stage of the disease." (PMID 12778073, 2003). "It has been shown that some types of tumour cells produce activated transforming growth factor beta-1 (TGF-beta 1)." (PMID 7669580, 1995). "Tumor cells communicated with immune cells via the TGFB1-TGFβR1/R2 axis, promoting immune evasion." (PMID 42198359, 2026). "Notably, this elevated cell cytolytic response remains substantially resistant to the immunosuppressive effects of TGFβ-1, a cytokine known to dampen NK cell activity and commonly present in the tumor microenvironment." (PMID 41986797, 2026). "Given the significantly attenuated TGFB1 expression levels in exp‐CAF2‐shENG cells, we speculated that the decreased TGF‐β1 production contributed to the suppression of primary tumor growth and metastasis by ENG reduction in CAFs." (PMID 40644310, 2025).
tumor (continued). "TGFB1 notably impacts tumor survival, migration, and metastasis across cancer types." (PMID 39817507, 2025). "Meanwhile, CellChat results inferred that tip cell expressing Tgfb acted on K tumour EP, and we also found in in vitro experiments that stimulating LKR cells using TGFβ1 could significantly enhance tumour cell invasion and migration." (PMID 41431249, 2025). "Furthermore, TGFβ1 activates RhoA in LECs, leading to lymphatic vessel contraction, increased permeability, and structural alterations, thereby facilitating tumor cell dissemination." (PMID 41041337, 2025). "Interestingly, PCLAF was primarily up-regulated in CAFs, while TGFB1 up-regulation was predominantly detected in tumor cells (FaDu and Tu212)." (PMID 41035818, 2025). "Tumor stromal cells showed higher TGFB1 production than normal cells (p < 0.0001)." (PMID 41373732, 2025). "This may explain that during tumour progression tumour cells promote tumour growth and metastasis by secreting TGFβ1 and activating neighboring ECs to express PLVAP." (PMID 41431249, 2025). "In contrast to prior studies that primarily focused on overall immune cell populations or the composition of the immune microenvironment, our investigation emphasizes the dynamic changes and functional heterogeneity of TGFβ1+ Tregs across different tumor grades." (PMID 40891683, 2025). "Therefore, we deduced that a small number of tip cells would express TGFβ1 acting on tumour cells at the early stage of tumour to enhance their invasiveness." (PMID 41431249, 2025). "To determine whether RT induces the expression of TGF‐β and VEGF, we analyzed the transcription level of Tgfb1, Tgfb2, Tgfb3, and Vegfa using RNA‐seq data of irradiated versus non‐irradiated 4T1 tumor tissues." (PMID 40470716, 2025). "Moreover, Tregs produce TGFB1 and interleukin-17 (IL-17) to promote CSCs properties toward tumor progression and invasion." (PMID 39981232, 2025). "Interestingly, plasma Tgfβ1 levels retained a significant predictive capability across these three tumor types." (PMID 41360769, 2025). "In tumor-derived stromal cultures, TGFB1 and TGFB2 levels were strongly correlated (r = 0.976)." (PMID 41373732, 2025). "Other cytokines and molecules in the tumour microenvironment (e.g., IL‐10, TGFβ‐1 and PGE) also regulate tumour‐associated myeloid cells, as they play significant roles in the functional polarisation of monocytes/macrophages into an immunosuppressive phenotype." (PMID 40434054, 2025). "These genes displayed consistent temporal expression changes within the corresponding Treg subsets, indicating a dynamic adjustment of immune regulatory mechanisms in the tumor microenvironment and underscoring the pivotal role of TGFβ1+ Tregs in immune evasion." (PMID 40891683, 2025). "Moreover, our research has revealed that the TGFβ1+ Treg subset plays a pivotal role in tumor immune evasion and the exhaustion of CD8+ T cell function." (PMID 40891683, 2025). "Among them, the TGFβ1/SMAD2/3 signaling pathway plays critical roles in tumor metastasis." (PMID 40291908, 2025). "This discrepancy may stem from TGFB1’s pleiotropic and context-dependent functions—it can act as a tumor suppressor in early PDAC stages by enforcing growth arrest, yet also promote late-stage progression via fibrosis and immune evasion." (PMID 40650134, 2025). "As a surrogate for tumor-driving factors from stromal cells, TGFB1 was added." (PMID 41209344, 2025). "We hypothesized that NAC and raloxifene could contribute to reduce TGFβ1 levels in the tumor microenvironment and therefore, combat short term resistance to PDT." (PMID 40384860, 2025). "The TGFB1 pathway is known to play a role in immune suppression and tumour progression." (PMID 40982354, 2025). "Furthermore, CCL17, another cytokine secreted by M2 macrophages, has been shown to be closely associated with tumor stemness and EMT in the TGFβ1 and Wnt/β‐catenin signaling pathways." (PMID 40529613, 2025).
tumor (continued). "Moreover, in advanced cancer, TGFβ1 promotes tumor progression through EMT, immune evasion, angiogenesis, ECM remodeling, and T cell differentiation." (PMID 40725832, 2025). "Increasing evidence suggests that the activation of the TGFβ1/SMAD signaling cascade in tumor cells promotes cell-cycle arrest, leading to the entry of tumor-propagating cancer cells into a quiescent state with decreased susceptibility to suffer cellular damage in response to therapeutic agents." (PMID 40384860, 2025). "Intercellular analysis revealed that some tip cells also expressed TGFβ1, which may act on adjacent tumour cells to enhance invasion during early tumour development." (PMID 41431249, 2025). "Additionally, the expression of TGFB1 was significantly elevated in tumor samples compared with that in normal liver tissues." (PMID 39838454, 2025). "The human tumor datasets of TCGA were used to identify possible links between TGFB1 mRNA expression and the signature of genes related to different biological pathways, including pathways that could orchestrate EV biogenesis, such as cholesterol homeostasis." (PMID 39910665, 2025). "It has been previously shown that b-catenin indeed plays a role in the regulation of L1CAM expression in colon cancer, and that in pancreatic cells, the upregulation of L1CAM is Slug-dependent and TGFb1-dependent and promotes tumor cell migration and chemoresistance." (PMID 40870967, 2025). "Due to resistant tumor subpopulations and soluble tumor microenvironment factors such as TGFβ1, the use of cytokines as agents to enhance the immune response against malignancies may not always be effective." (PMID 40710292, 2025). "It is worth mentioning that we observed that TGFB1 treatment could inhibit PCLAF expression in tumor cells." (PMID 41035818, 2025). "In contrast, TGFβ1 could have an immunosuppressive effect on NK cells due to its ability to induce the conversion of anti-tumor NK cells into pro-tumor ILC1s (type 1 lymphoid cells)." (PMID 40710292, 2025). "Besides CD90, another historical driver of tumor progression, particularly in the liver, is Transforming Growth Factor-beta 1 (TGF-β1)." (PMID 40507785, 2025). "Additionally, we provided evidence supporting the potential clinical value of Tgfβ1 as a marker of the MO-MDSC to PMN-MDSC ratio among tumor patients." (PMID 41360769, 2025). "Moreover, paracrine stimulation of TGFb1 from fibroblasts was more important for transformation to mesenchymal cancer cells than the activation of the TGFb1 signaling in the tumor cells themselves in coculture with fibroblasts." (PMID 40253402, 2025). "Transforming growth factor β1 (Tgfβ1) plays dual roles in tumor progression." (PMID 41360769, 2025). "Some studies suggest that TGFβ1 promotes ferroptosis and inhibits tumor growth." (PMID 39991579, 2025). "Notably,TGFβ1+ Tregs play a pivotal role in shaping the immunosuppressive tumor microenvironment in CRC." (PMID 40891683, 2025). "In addition, TGF-β1 secreted by M2-like TAMs enhances tumor immune escape and drug resistance by activating the TGFβ1-Smad2/3 pathway." (PMID 39757995, 2025). "These include NT5E (CD73) and ENTPD1 (CD39) which are involved in immunosuppressive adenosine signaling, LGALS1 (galectin-1) and TGFB1, which encode for anti-inflammatory cytokines, and CD274 (PD-L1), which binds to PD-1 to initiate an inhibitory signaling pathway in anti-tumor immune cells." (PMID 40277917, 2025). "Osteoclasts and tumor cells contribute to bone destruction, and neurotrophins, cytokines (IL-1β and TNFα), and other factors (ATP, TGFβ1, IGF-1, and sclerostin) play roles, suggesting potential intervention targets for improved pain management and enhanced patient quality of life." (PMID 38474093, 2024). "Similarly, the fluorescence overlap ratio of MCU/TGFb1 was elevated in the late-stage group compared to both the non-tumor and early-stage groups." (PMID 38632642, 2024).